EZH2 (enhancer of zeste 2 polycomb repressive complex 2 subunit)
Diseases named in the same sentence as EZH2 in open-access papers (continued):
Sharing a sentence is not in itself a finding about the gene and the disease.
tumor (continued). "EZH2 also has an important role in the function of T regulatory cells (Tregs), which are also involved in immune homeostasis and anti-tumor immunity." (PMID 27793053, 2016). "Our study was the first to evaluate the role of EZH2 in regulating mRNA and lncRNA expression in tumor by integrating ChIP sequencing and co-expressing analysis." (PMID 27835578, 2016). "Several other studies have reported DNA methylation and tumor suppressors in cancers marked with polycomb proteins enriched with EZH2 and H3K27me3." (PMID 27461342, 2016). "In the phthisical eye enucleated from a child with prior chemotherapy and orbital extension of IM, small foci of residual IM tumor cells are easily visible by EZH2 immunohistochemistry." (PMID 27842164, 2016). "Highly EZH2 protein expression level is also associated with the early pathogenesis and prognosis of NSCLC patients, and promotes tumor progression via regulating VEGF-A/AKT signaling." (PMID 26840083, 2016). "EZH2 suppression leads to apoptosis and sensitizes tumor cells to cisplatin-induced apoptosis via upregulation of PUMA expression." (PMID 27472460, 2016). "This is similar to some other transcription factors, such as EZH2, which can function as both a tumor suppressor and an oncogene in different types of cancers." (PMID 27224916, 2016). "As critical epigenetic and oncogenetic factors, increased expressions of DNMT1 and EZH2 have been shown in several cancer types including lung through silencing tumor suppressor genes via hypermethylation and other mechanisms." (PMID 27421653, 2016). "EZH2 is a histone methyltransferase whose functions in stem cells and tumor cells are well established." (PMID 27468692, 2016). "We also examined the anti-tumor effect of these EZH2 inhibitors on murine PTEN-null CRPC cell line PTEN-CaP8." (PMID 26657505, 2016). "BMI1, EZH2 and other PcG proteins can be targeted by pharmacological inhibitors of HDACs, which are known for tumor suppressive properties." (PMID 27105531, 2016). "Growing evidence has identified supports the SWI/SNF-PRC2/EZH2 axis as a powerful tumor suppressor/oncogene pathway." (PMID 27125524, 2016). "We subcutaneously injected 1×102, 1×103, 1×104, 1×105, or 5×106 tumor cells isolated from primary xenografts of the WT, control or EZH2 knockdown group into secondary nude mice." (PMID 27172794, 2016). "Previous report indicated that UHRF1 and EZH2 synergistically and independently silence tumor suppressors by methylation: UHRF1 induce methylation of tumor suppressor gene DNA CpGs and H3-K9me3, and EZH2 induce methylation of H3-K27." (PMID 27487138, 2016). "Numerous studies report that miR-124 targets an enhancer of zeste homolog 2 (EZH2), an important transcription factor involved in the proliferation and metastasis of tumor cells." (PMID 27240340, 2016). "Using an EZH2-specific antibody for immunohistochemistry, we semiquantitatively calculated the proportion of IM tumor cells positive for EZH2, and also assayed for EZH2 staining intensity." (PMID 27842164, 2016). "RNA interference of EZH2 suppressed tumor development and metastasis in vivo and microarray analysis of EZH2 knock down revealed an EZH2-maintained, undifferentiated, reversible phenotype in ES." (PMID 26623725, 2016). "The canonical role of EZH2 is mainly to transcriptionally silence of tumor suppressor genes which depends on PRC2." (PMID 27835578, 2016). "In particular, EZH2 regulates angiogenesis in the tumor microenvironment, where it is itself regulated by VEGF-miRNA-101 axis." (PMID 26416763, 2016). "Previously, our work and others have demonstrated the greater anti-tumor activity of etoposide combined with EZH2 inhibitors." (PMID 26973857, 2016). "This correlates with a high tumor proliferation index (Ki-67) and, due to EZH2 overexpression, a decrease in E-cadherin (cases #18 and #19)." (PMID 27705913, 2016).
tumor (continued). "Overexpression of EZH2 has been found to correlate with tumor aggressiveness, metastasis, and poor prognosis in numerous cancer types, including HCC." (PMID 26733151, 2016). "Further experiments with additional HPV+ and HPV- cell lines, in addition to primary cultures and in vivo models such as tumor explants would be important to further characterize the EZH2 inhibitors used in this study." (PMID 27793210, 2016). "Of 109 tumor tissue samples, 61 (55.9%) NSCLC cancers had high EZH2 expression, whereas only 9 (8.3%) had high expression in adjacent non-tumor tissues." (PMID 27472460, 2016). "Our previous study found that the expression level of EZH2 was higher in CRC tumor tissues than in the paired normal tissues using immunohistochemical analysis." (PMID 27706111, 2016). "Inhibition of EZH2 expression and activity, and thus loss of Polycomb target gene repression, is associated with HMCL growth inhibition and decreased tumor load and survival in a mouse model of MM." (PMID 26497210, 2016). "Genes with high coefficients were largely consistent among the ten tumor types, which is, EZH2 was either positively or negatively correlated with these genes in all ten tumors." (PMID 27835578, 2016). "Zhong et.al, demonstrated a statistically significant correlation between the overexpression of EZH2 and tumor proliferation, pathologic grade and nodal metastases in patients with oral tongue cancer." (PMID 27793210, 2016). "Enhancer of zeste homologue 2 (EZH2) is a potential independent mechanism for epigenetic silencing of tumor suppressor genes in cancer." (PMID 26683709, 2016). "A mechanistic study was able to demonstrate that NBAT-1 acts as a tumor suppressor by interacting with EZH2, a subunit of the global gene expression regulator PRC2 complex." (PMID 27608009, 2016). "Treatment with HDAC inhibitors results in EZH2 expression down-regulation in tumor cells, suggesting that PRC2 and HDACs collaborate in the epigenetic control of gene expression." (PMID 26497210, 2016). "In contrast, all of the corresponding non-tumor tissues showed weakly positive immunostaining of EZH2 protein." (PMID 26913601, 2016). "The proportion of IM cells staining positive for EZH2 was moderate to diffuse in each case, but occasionally varied within each tumor." (PMID 27842164, 2016). "EZH2 is frequently overexpressed in GC, and EZH2 levels are positively correlated with tumor size, depth of invasion, vessel invasion, lymph node metastasis, and clinical stage." (PMID 26799422, 2016). "More recently, it has been reported that EZH2 is significantly overexpressed in tumor cells from patients with chronic lymphoid leukemia compared with paired healthy B-cells." (PMID 26497210, 2016). "Reducing cellular EZH2 activity has previously been shown to negatively affect cell proliferation of certain tumor types." (PMID 27634879, 2016). "There is strong evidence that oncogenic signaling in a variety of human neoplasms leads to alteration of EZH2 transcriptional regulation promoting cancer cell proliferation and disease progression." (PMID 27793053, 2016). "Here, we show for the first time that LINC00152 promotes tumor cell cycle progression by binding to EZH2 and repressing p15 and p21 in GC." (PMID 26799422, 2016). "The strongest EZH2 expression was seen in 55 of 90 tumor samples (61.1%), but in only 1 of 90 adjacent tissues (1.1%)." (PMID 27882937, 2016). "For example, enhancer of zeste homologue 2 (EZH2) is over-expressed in several human tumours and accounts for the aggressiveness and unfavourable prognoses of various tumours." (PMID 27010768, 2016). "For instance, INK4B-ARF-INK4A, p57, bone morphogenetic protein receptor 1B, MyoD and RUNX3 are all negatively regulated by EZH2, which is critical for tumor cell proliferation and aggressiveness." (PMID 27259264, 2016).
tumor (continued). "There is convincing mechanicistic data confirming the oncogenic function of EZH2 related to PRC2 functioning (repression of tumor suppressor genes through H3K27me3) in several biological models." (PMID 27239242, 2016). "Furthermove, an inverse relationship was found between lncRNA XIST and miR-101, and knockdown of lncRNA XIST exerted its tumor-suppressive effects at least in part through regulating miR-101 to modulate EZH2 expression." (PMID 27620004, 2016). "The correlation between EZH2 expression and growth control of ES was suggested by both ES growth inhibition in vitro and delayed tumor development and metastases in mice induced by RNA interference-mediated inhibition of EZH2." (PMID 27471434, 2016). "EZH2 was highly expressed in the nuclei of illustrated tumor samples as compared with the same adjacent tissues in two representative staining samples." (PMID 27882937, 2016). "DAB2IP, a novel family of RasGTPase-activating protein family as a potent tumor suppressor, is epigenetically silenced, which is suppressed by EZH2 and other epigenetic machinery such as DNA methylation and histone acetylation." (PMID 27129174, 2016). "Interaction between EZH2 and lncRNAs in tumor also draws great attention to researchers in recent years." (PMID 27835578, 2016). "EZH2 inhibition using small molecule inhibitors shows potent anti-tumor effects and has minimal toxic effects in vivo." (PMID 26755663, 2016). "EZH2 was detected in all the tumor samples, most of them with variable EZH2 expression patterns (right)." (PMID 27317769, 2016). "The cell culture-based experiments confirmed the stemness traits and plasticity of E-MpM, and support the view that EZH2 is a druggable target in this tumor." (PMID 27705913, 2016). "After implanting U251 cells transfected with pJAX-EZH2 or control vector into the brains of immunocompromised mice, we observed that up-regulation of EZH2 promoted tumor formation and decreased the survival of tumor-bearing mice." (PMID 27259264, 2016). "The mechanisms of EZH2 aberration and the molecular pathways involved in the regulation of EZH2 abundance and activity in human neoplasms together with the development of novel therapeutic opportunities to target EZH2 are under intense investigation." (PMID 27793053, 2016). "Repression of EZH2 induced cell cycle arrest and inhibited tumor growth in vivo, by inhibition β-catenin signaling." (PMID 27385092, 2016). "In MM, EZH2 has previously been suggested to have oncogenic properties based on its overexpression and correlation of histone methyltransferase activity to tumor formation in vivo." (PMID 26755663, 2016). "Most importantly, it was this activity (and not proliferation rate) that correlated with enhanced tumor growth as only EZH2 GOF expressing cells displayed increased A375 tumor size in xenograft studies." (PMID 25671303, 2015). "In this study, we have determined the effects of honokiol through the repression of oncoprotein EZH2 and induction of tumor suppressor miR-143, on the UBC cell proliferation, survival, cancer stemness maintenance and cell migration in vitro and in vivo." (PMID 26484567, 2015). "Our in vitro studies suggested that EZH2 is the direct downstream target of miR-26a; therefore, we examined EZH2 protein expression in tumor tissues using IHC." (PMID 26587974, 2015). "EZH2 is frequently overexpressed in multiple tumor types, including BC, and plays multiple roles besides the well-recognized histone mark generation." (PMID 26580594, 2015).
tumor (continued). "The catalytic subunit of epigenetic regulator Polycomb repressive complex 2, EZH2, functions as a transcriptional repressor for the maintenance of DNA methylation and stable repression of specific genes, including many tumor suppressors." (PMID 25831237, 2015). "Prior studies suggest that Ezh2 can control cell proliferation in part through silencing of the Ink4a/Arf and p21 tumor suppressor loci." (PMID 26637281, 2015). "Apart from tumor size and clinical stage, EZH2 was differently expressed among the HNSCC samples with different histological types." (PMID 26378043, 2015). "EZH2 is often overexpressed in prostate and breast cancers, where it promotes tumor formation and progression and correlates with a poor prognosis." (PMID 26587974, 2015). "We propose that these observations reconcile contradictory data reporting inverse variations of EZH2 and H3K27me3 in several tumor types." (PMID 26637281, 2015). "In several epithelial cancers, overexpression of wild-type EZH2 has been found to promote tumor progression or metastasis." (PMID 26043758, 2015). "To better illustrate the role of EZH2 in HNSCC tumor growth, we established HNSCC xenograft tumor model using Cal27 cell lines." (PMID 26378043, 2015). "siRNA against EZH2 and SUZ12 were used because these targets have been directly linked to regulating miR-200b in neoplasia." (PMID 25884496, 2015). "To address the mechanism through which EZH2 inhibition effecting tumor cell apoptosis, we found that HNSCC cell showed spatially increase of cyto-Ca2+ and loss of ΔΨm was induced by DZNep treatment." (PMID 26378043, 2015). "On the contrary, nuclear EZH2 expression was significantly higher in the group of tumor samples (n = 165, mean EZH2: 2.76%, p ≤ 0.0005)." (PMID 26593398, 2015). "EZH2 is required for tumor progression in H3K27me3 dependent manner, and this can be blocked by EZH2 inhibitors, like GSK126 or EPZ-6438." (PMID 26378043, 2015). "Overexpressed EZH2 was proposed to participate in aberrant silencing of tumor suppressor genes such as DAB2IP, ADRB2, and SLIT2." (PMID 26637281, 2015). "EZH2 expression often correlates with tumor aggressiveness and serves as an independent prognostic indicator of survival in lung, prostate, ovarian, breast and renal cell carcinomas." (PMID 25671303, 2015). "Of note, EZH2 inhibition impairs tumor cell proliferation ability, cell cycle progression and anti-apoptisis potential in both cell lines and this suppressed Cal27 derived tumors’ growth in a xenograft model." (PMID 26378043, 2015). "For example in some myeloid disorders, missense mutations of EZH2 occur in loss of function of EZH212, indicating a possible tumor suppressive role in these tumor types." (PMID 26593398, 2015). "MiR-26a greatly suppresses the enhancer of zeste homolog 2 (EZH2), inhibits cell proliferation, blocks G1/S transition, and induces tumor cell apoptosis." (PMID 25815339, 2015). "We also investigated the effects of miR-101 level on EZH2 gene expression, a well-known tumor-promoting gene, recently described as an important miR-101 target." (PMID 25762643, 2015). "Regarding PRC2, we have recently demonstrated that elevated EZH2 expression promotes extensive gene expression rewiring leading to increased tumor recurrence and progression in human NMIBC." (PMID 26517683, 2015). "In agree with previous studies, human HNSCC displayed positive expression of EZH2 in tumor cell nuclei." (PMID 26378043, 2015). "Of note, honokiol treatment significantly decreased tumor growth in vivo by downregulation of EZH2 expression and other aggressiveness related protein levels." (PMID 26484567, 2015). "HNSCC with larger tumor size ( > 2cm) showed a higher positive rate of EZH2 comparing with the smaller tumor size group (≤2cm, χ2 = 7.980, P = 0.006)." (PMID 26378043, 2015). "We, therefore, propose that one underlying mechanism by which miR-31 suppresses tumor cell invasion is by directly targeting SOX4 and indirectly targeting EZH2 and HDAC3." (PMID 25644061, 2015).
tumor (continued). "Similar results were obtained by pharmacologically down-regulating EZH2, once again confirming the opposite functional roles of EZH2 and miR-101 in these tumor cells." (PMID 26251675, 2015). "We have shown that combined inhibition of EHMT1/2 and EZH2 increases growth inhibition in tumour cells over inhibition of only EHMT1/2 or EZH2 and results in re-expression of silenced genes." (PMID 26300989, 2015). "MiR-101 has been reported to exert tumor suppressor functions in several human cancers by modulating EZH2 expression." (PMID 26251675, 2015). "In vitro experiments revealed a significant (p ≤ 0.05) decrease of tumor cell proliferation using the EZH2 inhibitor GSK126." (PMID 26593398, 2015). "Because of the importance of EZH2-regulated miR-30d expression that modulates KPNB1 in MPNST cell survival and apoptosis in vitro and in vivo, pharmacological inhibition of EZH2 represents a promising therapeutic approach for this tumor type." (PMID 25890085, 2015). "Herein, we report that miR-101 is down-regulated in eRMS patients and in tumor cell lines compared to their controls showing an inverse pattern of expression with EZH2." (PMID 26251675, 2015). "We have recently shown that increased EZH2 protein is a common hallmark of NMIBC at high risk of recurrence and tumor progression." (PMID 26517683, 2015). "The immunohistochemical detection of Enhancer of zeste homologue 2 (EZH2) proved to be a useful tool to recognize the malignant nature of tumors in a wide variety of neoplasms." (PMID 26377323, 2015). "As member of the Polycomb-group family, EZH2 acts as transcription repressor of several cell cycle-related tumor suppressor genes such as CDKN1C through methylation of histone H3 on lysine 27 (H3K27)." (PMID 26110843, 2015). "Scrutiny of the top 30 genes identified a number of novel EZH2 target genes with possible tumor suppressor gene roles, including the ATF3 transcription factor; validated by ChIP-qPCR." (PMID 26304929, 2015). "By association with enhancer of zeste homolog 2 (EZH2), a well-established mediator of tumor metastasis, H19 upregulates Wnt/β-catenin signaling, which in turn represses E-cadherin expression." (PMID 26536864, 2015). "In reverse, several tumor suppressor miRNAs and proapoptotic miRNAs have been identified as the direct targets of EZH2." (PMID 26484567, 2015). "Altogether these results identify a yet unappreciated potential role for DLBCL mutations in stabilizing lncRNAs, perhaps helping epigenetic mechanisms such as those mediated by EZH2 in promoting lymphomagenesis and maintaining the tumor identity." (PMID 26521025, 2015). "Against this background, we investigated the expression of EZH2 in a large cohort of human pituitary glands and related tumor samples." (PMID 26593398, 2015). "On the other hand, the incidence of vascular invasion and poor tumor differentiation was higher in the high EZH2 group than in the EZH2 low group." (PMID 25226601, 2014). "EZH2 has been found to be involved in multiple biological processes, such as tumor proliferation, cell cycle, senescence, metastasis and angiogenesis." (PMID 25295088, 2014). "High staining of the tumor cells for H2AK119Ub1, EZH2, and Ring1B was found in most samples (55%, 60%, and 56% respectively)." (PMID 25431952, 2014). "The authors concluded that high expression of EZH2 correlates with tumor aggressiveness and adverse patient outcome in ESCC treated with definitive chemoradiotherapy." (PMID 25036033, 2014). "Enhancer of zeste homologue 2 (EZH2), as a member of the polycomb group of genes has important functions in tumor aggressiveness." (PMID 25159232, 2014). "More than 50% of the tumor cells showed a high expression of H2AK119Ub1, Ring1B, and EZH2, whereas more than 50% of the tumor cells showed a low level of H3K27Me3." (PMID 25431952, 2014).